SH3GLB1 (SH3 domain containing GRB2 like, endophilin B1)
Description:
May be required for normal outer mitochondrial membrane dynamics. Required for coatomer-mediated retrograde transport in certain cells (By similarity). May recruit other proteins to membranes with high curvature. May promote membrane fusion. Involved in activation of caspase-dependent apoptosis by promoting BAX/BAK1 activation. Isoform 1 acts proapoptotic in fibroblasts (By similarity). Involved in caspase-independent apoptosis during nutrition starvation and involved in the regulation of autophagy. Activates lipid kinase activity of PIK3C3 during autophagy probably by associating with the PI3K complex II (PI3KC3-C2). Associated with PI3KC3-C2 during autophagy may regulate the trafficking of ATG9A from the Golgi complex to the peripheral cytoplasm for the formation of autophagosomes by inducing Golgi membrane tubulation and fragmentation. Involved in regulation of degradative endocytic trafficking and cytokinesis, probably in the context of PI3KC3-C2. Isoform 2 acts antiapoptotic in neuronal cells; involved in maintenance of mitochondrial morphology and promotes neuronal viability (By similarity).
Synonyms: Bif-1; KIAA0491; CGI-61; PPP1R70; dJ612B15.2
Tractability: Antibody: UniProt places it where antibodies can reach, with high confidence. PROTAC: ubiquitination databases record sites on it; its protein half-life has been measured.
Gene: Protein-coding gene on chromosome 1 (86,704,520 to 86,748,184, forward strand). Ensembl gene ENSG00000097033.
Subcellular location: Cytoplasm; Golgi apparatus membrane; Mitochondrion outer membrane; Cytoplasmic vesicle, autophagosome membrane; Midbody
Subcellular location (Human Protein Atlas): Cytosol
Gene Ontology:
Molecular function: cadherin binding; identical protein binding; protein binding; protein homodimerization activity; protein-macromolecule adaptor activity; fatty acid binding; lysophosphatidic acid acyltransferase activity; phosphatidylinositol 3-kinase activator activity
Biological process: autophagic cell death; cellular response to amino acid starvation; cellular response to glucose starvation; membrane fission; positive regulation of autophagosome assembly; positive regulation of autophagy; positive regulation of establishment of protein localization to mitochondrion; positive regulation of membrane tubulation; positive regulation of protein-containing complex assembly; protein localization to vacuolar membrane; receptor catabolic process; regulation of cytokinesis; regulation of protein stability; endocytosis; membrane organization; regulation of macroautophagy
Cellular component: autophagosome membrane; cytoplasm; cytosol; Golgi membrane; midbody; protein-containing complex; membrane; mitochondrial outer membrane
Genetic constraint (gnomAD): Loss-of-function variants: 10 observed, 25.9 expected, observed/expected ratio (o/e) 0.39, 90% interval 0.24 to 0.65. The upper end of that interval is the gene's LOEUF score, 0.65, which puts it in group 2 of 6, group 1 being the genes least tolerant of losing a copy. Missense variants: 264 observed, 328.13 expected, observed/expected ratio (o/e) 0.8, 90% interval 0.73 to 0.89. Synonymous variants: 98 observed, 114.27 expected, observed/expected ratio (o/e) 0.86, 90% interval 0.73 to 1.01.
Homologues: Orthologues: chimpanzee SH3GLB1 (100% identical), macaque SH3GLB1 (99% identical), rabbit SH3GLB1 (98% identical), guinea pig SH3GLB1 (97% identical), mouse Sh3glb1 (96% identical), dog SH3GLB1 (95% identical), pig SH3GLB1 (95% identical), rat Sh3glb1 (95% identical), tropical clawed frog sh3glb1 (82% identical), zebrafish sh3glb1a (76% identical), zebrafish sh3glb1b (73% identical), Drosophila melanogaster Dlish (14% identical), and 2 more. Paralogues in human: SH3GLB2 (65% identical), SH3GL1 (29% identical), SH3GL2 (25% identical), SH3GL3 (25% identical), SH3D19 (17% identical), SH3RF3 (17% identical), SH3RF1 (16% identical), SORBS1 (16% identical), SORBS2 (16% identical), SORBS3 (13% identical), SH3RF2 (12% identical), NCF4 (11% identical).
Diseases named in the same sentence as SH3GLB1 in open-access papers:
SH3GLB1 is named in the same sentence as 23 diseases in open-access papers, as found by Europe PMC text mining. Sharing a sentence is not in itself a finding about the gene and the disease. The quoted sentences say what the papers report.
glioma (7 papers, 2017 to 2022). A benign or malignant brain and spinal cord tumor that arises from glial cells (astrocytes, oligodendrocytes, ependymal cells). "We observed that gliomas with high risk scores expressed SH3GLB1, whereas those with low risk scores expressed MAPK8IP1." (PMID 28977840, 2017). "Analysis using a Cox proportional hazard regression model showed that MAPK8IP1 and SH3GLB1, two autophagy-related genes, were associated with the prognostic signature for glioma." (PMID 28977840, 2017). "And SH3GLB1, as the autophagy-related gene, is associated with glioma prognosis." (PMID 33042807, 2020). "Knockdown of SH3GLB1 inhibits glioma cell proliferation, migration and invasion, and improves sensitivity to temozolomide." (PMID 33042807, 2020). "We observed that treating SH3GLB1 downregulated LN229 glioma cells with 100μM TMZ suppressed glioma cell proliferation and invasion." (PMID 28977840, 2017). "We demonstrated that MAPK8IP1 overexpression and SH3GLB1 knockdown inhibited the proliferation, migration and invasion of glioma cells and increased sensitivity to Temozolomide." (PMID 28977840, 2017). "We also identified two genes, MAPK8IP1 and SH3GLB1, which precisely predicted clinical outcomes of glioma patients." (PMID 28977840, 2017). "We identified two genes, MAPK8IP1 and SH3GLB1 that accurately predicted the clinical outcome of glioma patients." (PMID 28977840, 2017). "MAPK8IP1 overexpression and SH3GLB1 knockdown inhibited glioma cell proliferation, migration and invasion, and improved Temozolomide sensitivity." (PMID 28977840, 2017). "We transfected three SH3GLB1 siRNAs in LN229 glioma cells and analyzed SH3GLB1 mRNA levels by qRT-PCR." (PMID 28977840, 2017). "We demonstrated that MAPK8IP1 overexpression and SH3GLB1 downregulation increased the sensitivity of glioma cells to Temozolomide treatment." (PMID 28977840, 2017). "This suggested that MAPK8IP1 played a tumor suppressor role, whereas SH3GLB1 was a oncogene in glioma." (PMID 28977840, 2017). "Then, we examined the effects of SH3GLB1 downregulation on proliferation of LN229 glioma cells by CCK-8 assay." (PMID 28977840, 2017). "Concurrently, down-regulation of another autophagy-related gene SH3GLB1 also inhibited proliferation, migration and invasion of glioma cells." (PMID 28977840, 2017). "This suggested that SH3GLB1 downregulation increased the sensitivity of glioma cells to Temozolomide." (PMID 28977840, 2017). "We also showed that MAPK8IP1 overexpression and SH3GLB1 knockdown inhibited proliferation, migration and invasion of glioma cells in addition to improving sensitivity to TMZ treatment." (PMID 28977840, 2017). "We observed that SH3GLB1 was up-regulated in glioma samples from the CGGA Batch 1 dataset." (PMID 28977840, 2017). "Furthermore, we investigated the role of MAPK8IP1 and SH3GLB1 on glioma cell proliferation, migration, invasion and their effect on Temozolomide treatment." (PMID 28977840, 2017). "Also, transcription factors interacting with MAPK8IP1 and SH3GLB1 were involved in multiple pathways like TGF, Hedgehog and WNT/Wingless signaling, which were associated with glioma." (PMID 28977840, 2017). "Furthermore, there is a growing body of literature that recognizes the importance of potential applications of autophagy related proteins, including LC3, ATG7, ATG5, Beclin1, and SH3GLB1, as prognostic biomarkers in some tumors, like glioma, breast cancer, and colon cancer." (PMID 33510635, 2020). "Therefore, we investigated the effect of SH3GLB1 downregulation in LN229 glioma cells." (PMID 28977840, 2017). "Glioma patients from the CGGA batches 1 and 2, GSE4412 and TCGA datasets could be divided into high- and low-risk groups with different survival times based on levels of MAPK8IP1 and SH3GLB1 expression." (PMID 28977840, 2017). "Given that SH3GLB1 can alter mitochondrial functions, IPA for the RNA transcriptome of paired recurrent and treatment-naïve high-grade glioma samples was used to pinpoint related pathways." (PMID 35831908, 2022).
glioma (continued). "This suggested that the two autophagy related genes, SH3GLB1 and MAPK8IP1 had opposite effects on glioma progression." (PMID 28977840, 2017). "We analyzed expression of SH3GLB1 in five glioma cell lines using qRT-PCR and observed that SH3GLB1 was upregulated in LN229 glioma cells compared to oligodendrocytes." (PMID 28977840, 2017). "Our data suggested that both SH3GLB1 and MAPK8IP1 interacted with other autophagy-related components and were involved in the pathogenesis of glioma." (PMID 28977840, 2017).
Sepsis (4 papers, 2020 to 2023). Sepsis is defined as life-threatening organ dysfunction caused by a dysregulated host response to infection. "According to a recent study, SH3GLB1 has diagnostic significance for pediatric sepsis." (PMID 37701780, 2023). "In addition, there was association with FGF13 through BST1 and PCOLCE2 through SH3GLB1 in pediatric sepsis." (PMID 32318053, 2020). "The results showed that IKBKB and PRKCQ were significantly downregulated in the sepsis group, while SH3GLB1 and WIPI1 were significantly upregulated." (PMID 37701780, 2023). "The four key genes that were identified to have both significant diagnostic and prognostic value in sepsis (IKBKB, PRKCQ, WIPI1, and SH3GLB1) were validated by RT-qPCR in whole blood samples obtained from sepsis patients and healthy controls." (PMID 37701780, 2023). "Another study using GEO data identified SH3GLB1, PGS1, and RAB31 as diagnostic markers for pediatric sepsis, a possible risk factor for KD pathogenesis." (PMID 36042431, 2022).
colorectal cancer (2 papers, 2013 to 2021). A primary or metastatic malignant neoplasm that affects the colon or rectum. "Interestingly, another study provided evidence that lncRNA RP4 competitively bound to miR-7-5p to elevate the expression of SH3GLB1 gene, thus repressing the biological processes of colorectal cancer." (PMID 33958701, 2021).
COVID-19 (2 papers, 2021 to 2022). A disease caused by infection with severe acute respiratory syndrome coronavirus 2. "In addition, we deployed validation experiments for local splicing changes of 6 genes (CD74, LRRFIP1, SH3GLB1, MACF1, RPS24 and PDLIM5) between 9 COVID-19 cases and 10 controls by semiquantitative reverse transcription (RT)-PCR." (PMID 35421082, 2022).
glioblastoma (2 papers, 2022 to 2026). The most malignant astrocytic tumor (WHO grade IV). "Characterizing SH3GLB1 in glioblastoma may help develop new therapeutic strategies against this disease in the future." (PMID 35831908, 2022).
atherosclerosis (1 paper, 2022). A disease characterized by the build-up of fatty material and calcium deposition in the arterial wall resulting in partial or complete occlusion of the arterial lumen. "Finally, SH3GLB1 has been implicated in apoptotic and autophagy pathways, but no studies have directly assessed its function in atherosclerosis." (PMID 35419441, 2022).
lung carcinoma (1 paper, 2014). "Dominant overexpression of Sh3glb1, Tm4sf1 or Csf1 in chromosome 3 of TCs is mainly associated with tumour promotion in lung cancer, while most down-expression of Pde5 may be involved in the development of pulmonary fibrosis and other acute and chronic interstitial lung disease." (PMID 25278030, 2014).
lymphoma (1 paper, 2022). A malignant (clonal) proliferation of B- lymphocytes or T- lymphocytes which involves the lymph nodes, bone marrow and/or extranodal sites. "For example, mice with biallelic deletion of Bif-1 (also known as SH3GLB1), which is involved in vesicle formation and membrane dynamics, developed spontaneous tumors and lymphomas." (PMID 35884904, 2022).
melanoma (1 paper, 2022). A malignant, usually aggressive tumor composed of atypical, neoplastic melanocytes. "It has been reported that downregulation of SH3GLB1 contributed to tumorigenesis by upregulating mitochondrial function in melanoma cells." (PMID 35831908, 2022).
tumor (16 papers, 2013 to 2026). "SH3GLB1/BIF1, which joins the BECN1 complex through UVRAG, is also a tumor suppressor; loss of SH3GLB1 inhibits autophagy while promoting tumorigenesis." (PMID 34829881, 2021). "In addition, the data demonstrated that the loss of SH3GLB1 in primary TMZ-R cells disturbed tumor sphere formation." (PMID 37525108, 2023). "SH3GLB1 modulation could determine tumor susceptibility to TMZ." (PMID 35831908, 2022). "TMZ combined with a redox modulator reduced resistant tumor cell growth (about 2/3 reduction of tumor size; p < 0.05) and suppressed SH3GLB1 and autophagy levels in animal models." (PMID 41613801, 2026). "Our findings on the effects of SH3GLB1 on the cells will help explain tumor resistance formation." (PMID 37525108, 2023). "Nonetheless, under certain circumstances, SH3GLB1 can enhance tumor migration and metastasis." (PMID 35831908, 2022). "Finally, in animal models, resistant tumor cells with SH3GLB1 knockdown became resensitized to the anti-tumor effect of TMZ, including the suppression of TMZ-induced autophagy and OXPHOS." (PMID 35831908, 2022). "Similarly, mice with either a monoallelic deletion for autophagy and Beclin1 regulator 1 (Ambra1) or a biallelic deletion for SH3 Domain Containing GRB2 Like, Endophilin B1 (SH3GLB1, aka Bif-1) revealed higher rates of spontaneous tumor incidence." (PMID 33224954, 2020). "Interestingly, previous reports have shown that SH3GLB1 functions as a tumor suppressor and pro-apoptotic factor." (PMID 24039573, 2013). "Therefore, we propose that SH3GLB1 participate in the impact on tumor-initiating cells (TICs)." (PMID 37525108, 2023). "SH3GLB1—SH3GLB1 (SH3 domain GRB2-like endophilin B1), also known as Bif-1 and endophilin B1, is a tumor suppressor gene of the endophilin protein family." (PMID 38304289, 2023). "Single-cell transcriptome analysis of clinical samples suggested that SH3GLB1 and the altered gene levels of oxidative phosphorylation (OXPHOS) were related to subsets expressing a tumor-initiating cell signature." (PMID 35831908, 2022). "Accordingly, a higher level of SH3GLB1 and enhanced autophagy were inherited in CD133+ tumor cells." (PMID 35831908, 2022).
SH3GLB1 also shares sentences with these, for which no sentence is quoted: cancer (5 papers); breast carcinoma (2); Parkinson disease (2); cholangiocarcinoma (1); colon adenocarcinoma (1); colon cancer (1); gastric cancer (1); Insulin resistance (1); ischemic stroke (1); myocardial infarction (1); prostate carcinoma (1); pulmonary fibrosis (1); synucleinopathy (1).